EID2 (EP300 interacting inhibitor of differentiation 2)
Description:
Interacts with EP300 and acts as a repressor of MYOD-dependent transcription and muscle differentiation. Inhibits EP300 histone acetyltransferase activity. Acts as a repressor of TGFB/SMAD transcriptional responses. May act as a repressor of the TGFB/SMAD3-dependent signaling by selectively blocking formation of TGFB-induced SMAD3-SMAD4 complex.
Synonyms: EID-2; CRI2; MGC20452
Tractability: No criterion of Open Targets' tractability assessment is met for any kind of drug.
Gene: Protein-coding gene on chromosome 19 (39,538,707 to 39,540,161, reverse strand). Ensembl gene ENSG00000176396.
Subcellular location: Nucleus
Subcellular location (Human Protein Atlas): Nucleoplasm; Centrosome
Gene Ontology:
Molecular function: protein binding; SMAD binding; transcription corepressor activity
Biological process: negative regulation of SMAD protein signal transduction; negative regulation of transcription by RNA polymerase II; negative regulation of transforming growth factor beta receptor signaling pathway; regulation of cell population proliferation; transforming growth factor beta receptor complex assembly; negative regulation of DNA-templated transcription
Cellular component: nucleoplasm; nucleus
Genetic constraint (gnomAD): Loss-of-function variants: 1 observed, 3.55 expected, observed/expected ratio (o/e) 0.28, 90% interval 0.099 to 1.29. That is too few expected variants to judge how well the gene tolerates losing a copy. Missense variants: 250 observed, 278.8 expected, observed/expected ratio (o/e) 0.9, 90% interval 0.81 to 1. Synonymous variants: 112 observed, 123.47 expected, observed/expected ratio (o/e) 0.91, 90% interval 0.78 to 1.06.
Homologues: Orthologues: chimpanzee EID2 (99% identical), macaque EID2 (98% identical), mouse Eid2 (78% identical), rat Eid2 (78% identical), guinea pig EID2 (73% identical), dog EID2 (66% identical), pig EID2 (58% identical). Paralogues in human: EID2B (31% identical), EID1 (23% identical).
Diseases named in the same sentence as EID2 in open-access papers:
EID2 is named in the same sentence as 2 diseases in open-access papers, as found by Europe PMC text mining. Sharing a sentence is not in itself a finding about the gene and the disease. The quoted sentences say what the papers report.
colorectal cancer (1 paper, 2024). A primary or metastatic malignant neoplasm that affects the colon or rectum. "Previous studies demonstrated that a high expression of EID2 in colorectal cancer acts as a favourable prognostic marker." (PMID 38051091, 2024).
EID2 also shares sentences with these, for which no sentence is quoted: breast carcinoma (1 paper).